ATP5MC1P1 (ATP synthase membrane subunit c locus 1 pseudogene 1)
Synonyms: formerly ATP5GP3; ATP5G1P1
Gene: Transcribed processed pseudogene on chromosome 14 (105,536,861 to 105,537,239, reverse strand). Ensembl gene ENSG00000230157.
Diseases named in the same sentence as ATP5MC1P1 in open-access papers:
ATP5MC1P1 is named in the same sentence as 1 disease in open-access papers, as found by Europe PMC text mining. Sharing a sentence is not in itself a finding about the gene and the disease. The quoted sentences say what the papers report.
leiomyoma (2 papers, 2023). A well-circumscribed benign smooth muscle neoplasm characterized by the presence of spindle cells with cigar-shaped nuclei, interlacing fascicles, and a whorled pattern. "Among these genes, ATP5MC1P1 was minimally altered in the White group (Leiomyoma/paired Myometrium) while significantly increased in the Black group." (PMID 37686244, 2023).